VIM (vimentin)
Diseases named in the same sentence as VIM in open-access papers (continued):
Sharing a sentence is not in itself a finding about the gene and the disease.
pancreatic cancer (continued). "Multifluorescent staining of pancreatic cancer tissues was conducted using antibodies against CD4 (white), CD8 (light blue), CD20 (pink), FOXP3 (red), VIM (green), and panCK (yellow), along with 4',6-diamidino-2-phenylindole, dihydrochloride (DAPI)." (PMID 40303346, 2025). "In the present study, the gene expression of key players in EMT—CDH1 and VIM—and the MAPK/ERK pathway—EGFR, ERK1, ERK2, c-Jun, and c-Fos—was assessed in paired healthy and neoplastic tissues of the same pancreatic cancer cohort." (PMID 40305202, 2025). "(A) Three different lineages of KPC pancreatic tumor cells (derived from KrasG12Dp53R172HPdx1-Cre mice) were obtained and stained for DAPI (blue; nucleus), E-cadherin (green; epithelial), and vimentin (red; mesenchymal)." (PMID 39656086, 2024). "In pancreatic cancer cells, ILF2 overexpression increases migration and invasion by regulating genes involved in epithelial-mesenchymal transition, such as upregulating vimentin (VIM) and fibronectin 1 (FN1) while downregulating cadherin 1 (CDH1/E-cadherin)." (PMID 39735599, 2024). "The results also emphasized that utilizing both epithelial (EpCAM) and mesenchymal (vimentin) antibodies with the lateral magnetophoretic microseparator significantly enhanced CTC isolation efficiency for both prostate and pancreatic cancer patients." (PMID 37345161, 2023). "Immunoreactivity of tumor tissues showed that vimentin and α-SMA were downregulated in Robinin treated mice, in which indicated that Robinin can partially inhibit development of pancreatic cancer." (PMID 38110966, 2023). "When pancreatic cancer cells were treated with the MS extract, the expression of MMP9, β-catenin, and vimentin decreased in a concentration-dependent manner, and the phosphorylation of STAT3 also decreased." (PMID 37550432, 2023). "In vitro experiment by our group demonstrated that the inhibition of B7-H4 increased cell-cell adhesion, decreased the formation of pseudopodia, increased the expression of E-cadherin, and decreased the expression of vimentin and CD44 in pancreatic cancer." (PMID 36217128, 2022). "After Numb PRRL specific knockdown, the expression of E-cadherin was up-regulated, while the expression of N-cadherin, Vimentin, Fibronectin, Snail2 and ZEB1 were down-regulated, suggesting that Numb PRRL can promote EMT in pancreatic cancer cells." (PMID 35345586, 2022). "Interstitial biomarkers such as Twist and Vimentin have been found advantageous to detection of aggressive CTC in lung, breast, and recently, pancreatic cancers in fluorescence immunohistochemical (IHC) staining and microscopy-based selection methods." (PMID 35316296, 2022). "Knockdown of NR5A2 in pancreatic cancer decreased the expression of FGB, TWIST, SNAIL, MMP9, MMP3, MMP2, and Vimentin, as well as increased the expression of the epithelial markers β-catenin and E-cadherin." (PMID 34277436, 2021). "Supporting these in vitro observations, in pancreatic cancer samples, KLF4 correlated positively with E-cadherin and negatively with vimentin and Cav-1, a direct transcriptional target of KLF4 that can inhibit EMT in pancreatic cancer." (PMID 34680284, 2021). "Further, two subpopulations of circulating hybrid cells (CHCs) were serendipitously discovered and labeled as CHC-1 (DAPI+/CD45+/E-cadherin+/vimentin-) and CHC-2 (DAPI+ /CD45+/E-cadherin+/vimentin+) in the peripheral blood of pancreatic cancer patients." (PMID 33042268, 2020). "In gemcitabine-resistant pancreatic cancer cells (MiaPaCa-2), DIM upregulated the expression of E-cadherin and suppressed zinc finger E-box binding homeobox 1 (ZEB1), vimentin, and slug, leading to a reversal of epithelial-to-mesenchymal transition." (PMID 35582221, 2020). "In the primary pancreatic tumor, the Fsp1/tdTomato‐positive cancer cells with a partial EMT program were also positive for other mesenchymal markers including αSMA, vimentin, and Zeb1." (PMID 30120146, 2018).
pancreatic cancer (continued). "1,25D3 or its analog MART-10 inhibit epithelial-mesenchymal transition (EMT) in pancreatic cancer BxPC-3 and PANC cells by down-regulating the expression of Snail, Slug and vimentin, which is accompanied by decreased migration and invasion." (PMID 28947955, 2017). "By comparing various wild-type pancreatic cancer cell lines, we determined which have a higher expression level of HNRNPA2B1 accompanied by the higher expression of N-cadherin and vimentin and lower expression of E-cadherin." (PMID 28077929, 2017). "AURKA inhibition reduced the levels of N-cadherin, CD44, vimentin, MMP-2, Slug, and Snail, but increased E-cadherin levels in pancreatic cancer cell lines." (PMID 28193222, 2017). "Overexpression of miR-29a resulted in an increase in epithelial marker, E-cadherin, and reduction in mesenchymal marker, Vimentin, indicating that reintroduction of miR-29a induces mesenchymal–epithelial transition (MET) in pancreatic cancer cells." (PMID 27626694, 2016). "Our results showed that the expression of mesenchymal molecular markers (vimentin, snail and slug) were decreased by ORI, whereas the expression of E-cadherin increased, indicating that ORI affects the EMT process in pancreatic cancer cells." (PMID 27453691, 2016). "Notch-1 signaling is an important pathway to upregulate the expression of EMT markers, ZEB1 and 2, Slug and vimentin, leading to the EMT, migration and drug resistance of pancreatic cancer cells." (PMID 27231938, 2016). "Conversely, knockdown of either PHLPP isoform decreased E-cadherin whereas increased vimentin expression, suggesting that PHLPP downregualtion promotes EMT in pancreatic cancer cells." (PMID 26760962, 2016). "Activated primary PSCs isolated from pancreatic cancer tissues were verified by immunofluorescence staining for α-SMA and vimentin." (PMID 25609203, 2015). "In pancreatic cancer cells, overexpression of TAZ markedly decreased the expression of E-cadherin but increased the expression of vimentin." (PMID 26416426, 2015). "We found the expressions of N-cadherin, vimentin and ZEB1 were up-regulated, while the expression of E-cadherin exhibited down-regulation at mRNA levels in CSCs of pancreatic cancer cell line PANC-1." (PMID 24521357, 2014). "Western blot analysis further confirmed that Wnt5a-overexpressing pancreatic cancer cells undergo an EMT, as evidenced by an increase in the expression of vimentin and snail and a concomitant reduction in the E-cadherin expression." (PMID 24156409, 2013). "We found that the number of both vimentin- and α-SMA-positive cells was decreased in tumors from the Shi-Re and Pi-Xu ZHENG models of pancreatic cancer compared with the control tumor, while tumors from the Xue-Yu model exhibited no changes in CAF activity." (PMID 22690248, 2012). "Acquisition of gemcitabine-resistant phenotype of pancreatic cancer cells is accompanied by the elevated notch activity, whose silencing by siRNA attenuates the EMT phenotype such as vimentin, ZEB1, Slug, and Snail expression." (PMID 22934011, 2012). "In summary, knockdown of STIP1 and VIM by siRNA resulted in decreased invasion and proliferation (STIP1) in the highly invasive pancreatic cancer cell line, Clone #3." (PMID 19216797, 2009). "At a concentration of 30 μM, NSYSU-115 consistently reduced vimentin expression by half across various pancreatic cancer cell lines, regardless of the treatment duration." (PMID 40762406, 2025). "In addition, the knockdown of KIFC1 inhibited N-cadherin and Vimentin expression and promoted E-cadherin expression, indicating that KIFC1 knockdown suppressed the EMT capacity of pancreatic cancer cells." (PMID 40612867, 2025). "In pancreatic cancer, PUS7 knockdown significantly suppressed the migratory and invasive abilities of pancreatic cancer cells, increased E-cadherin levels, and reduced V-cadherin and Vimentin expression." (PMID 40940790, 2025).
pancreatic cancer (continued). "A core biopsy of the pancreatic tumor showed atypical spindle cell morphology with positive staining for vimentin, characteristic of mesenchymal differentiation with no apparent epithelial features." (PMID 39594178, 2024). "A recent study in pancreatic cancer shows that the increased invasion of TAM2s can promote the EMT process of pancreatic cancer by activating TLR4/IL-10 signaling pathway in cancer cells, reducing E-cadherin and increasing the expression of Vimentin." (PMID 38693304, 2024). "DKO cell lines formed pancreatic tumors in mice, but their histological features were distinct from SMAD4 or TGFBR2 single knockouts as they produced mixed epithelial/mesenchymal morphologies with cells expressing both E-cadherin and vimentin." (PMID 38573819, 2024). "In contrast, it was found that the expression of snail, vimentin, and CD31 was increased in the Balb/C nude mice model, suggesting that calycosin may act as an anti‐cancer therapeutic agent by preventing pancreatic cancer cell proliferation." (PMID 38230908, 2024). "To further verify that COL11A1 promoted the EMT process in pancreatic cancer cells by activating the AKT/GSK-3β/Snail signaling pathway, we first detected the expression levels of E-cad, N-cad, VIM, and MMP-2/9 in PANC-1 cells with different treatments by Western blotting." (PMID 35327583, 2022). "For instance, in pancreatic tumors, the expression of SOX9 positively correlates with the expression of epithelial phenotype genes (CDH1, KRT7, KRT18, and KRT19) and negatively correlates with the expression of the mesenchymal phenotype gene VIM." (PMID 35884771, 2022). "In pancreatic cancer, HIF-1α recruits histone deacetylase 1 (HDAC1) to the promoter of miR-548an, which transcriptionally suppresses miR-548an expression and subsequently upregulates vimentin, which facilitates pancreatic tumorigenesis." (PMID 34884541, 2021). "Functional analysis showed that NR3C2 may inhibit pancreatic cancer cell metastasis by reducing EMT, with an induction in E-cadherin and a decrease in ZEB1, N-cadherin, and vimentin." (PMID 34249704, 2021). "Based on our current data and previous studies, we hypothesize that KrasG12D, PI3K, ERK, JNK, p38MAPK, vimentin, lncRNA MALAT1, lncRNA SNHG1, and lncRNA RP11-363N22.3 targeted by hsa-miR-143-3p may play crucial roles in pancreatic cancer." (PMID 33643376, 2021). "Meanwhile, vimentin and N-cadherin levels were found partially decreased and other tested markers were not apparently affected in Mint3-depleted pancreatic cancer cells." (PMID 32826949, 2020). "Our results showed that c-Myc knockdown could inhibit the proliferation, invasion, and migration of pancreatic cancer cells, and induce EMT with the upregulation of E-cadherin and downregulation of vimentin." (PMID 32362830, 2020). "In a pancreatic cancer cells experiment, exogenous overexpression of EZH2 resulted in increased expression of the mesenchymal marker Vimentin and decreased epithelial marker E-cadherin level, while EZH2 knockdown resulted in decreased expression of Vimentin and increased expression of E-cadherin." (PMID 32723346, 2020). "In pancreatic cancer cells and mouse xenografts, EGCG alone and in combination with gemcitabine prevented the “Cadherin Switch” as well as downregulated expression of TCF8/ZEB1, Vimentin, and β-Catenin, thus reducing the mesenchymal phenotype." (PMID 31405071, 2019). "Interestingly, vimentin (VIM) and αSMA (ACTA2) that we showed to co-localize with integrin α11 in the pancreatic cancer tumors also displayed increased expression in this tumor tissue." (PMID 31159419, 2019). "According to previous study, mesenchymal markers such as vimentin was overexpressed in the poorly differentiated and not in the well-differentiated pancreatic carcinomas among the overall 11.8% of positive staining of vimentin." (PMID 29416615, 2018).
pancreatic cancer (continued). "Indeed, in the setting of pancreatic cancer, PAR-1 also coincides with the expression pattern of the stromal markers, such as vimentin, collagen I and α-SMA." (PMID 28173772, 2017). "In pancreatic cancer, it has been reported that patients with absence of E-cadherin expression or the expression of vimentin had poorer prognosis than patients with the differentiated type." (PMID 27067801, 2016). "Especially, in pancreatic cancer, the expression of EMT markers such as Ncadherin, Vimentin, and transcription factors including ZEB1, Snail, and Twist have been increased in surgically resected pancreatic cancer sepecimens but not in the normal noncancerous pancreatic tissue." (PMID 27793006, 2016). "Immunohistological analysis demonstrated that Wnt5a-overexpressing tumors exhibited increased expression of vimentin and decreased expression of E-cadherin, indicative of the occurrence of EMT, compared to control tumors derived from empty vector-transfected pancreatic cancer cells." (PMID 24156409, 2013). "However, co-culturing of pancreatic cancer cells with PSC induced a fibroblast-like morphology, increased expression of Snail and vimentin, decreased E-cadherin levels, and enhanced migration, all indicative of an EMT." (PMID 24213498, 2012). "As vimentin is highly expressed in stromal fibroblasts it is not likely to be useful as a marker for differentiating pancreatic cancers from pancreatitis, but interestingly autoantibodies to this protein have been recently reported." (PMID 21448168, 2011). "Moreover, it was shown that the number of solitary infiltrating pancreatic carcinoma cells is an independent adverse prognostic factor and correlates with EMT markers such as decreased E-cadherin and increased vimentin expression." (PMID 24281218, 2010). "The high expression levels of VIM in our invasive cell line could represent a marker for the epithelial to mesenchymal transition (EMT), in agreement with previous pancreatic cancer studies." (PMID 19216797, 2009). "Specifically, we observed elevated levels of MAPK (p-ERK-T202-Y204), Vimentin, YAP (pS127), AMPK (pT172), eIF4G, Myosin-IIa (pS1943), Stat3 (pY705) and B-Raf (pS445), suggesting that M2 macrophage-derived exosomes induce various oncogenic signaling pathways in pancreatic cancer cells." (PMID 40624025, 2025). "Further investigations are needed to determine whether vimentin inhibitors have therapeutic effects in patients with PDAC with low PBRM1 expression, poorly differentiated PDAC, squamous molecular subtype PDAC, or undifferentiated pancreatic carcinoma." (PMID 40454484, 2025). "Conversely, budesonide reduced the expression of the mesenchymal markers VIMENTIN and FIBRONECTIN (FN1) both in PDAC and PANC1 cells, providing molecular support to the hypothesis that budesonide induces epithelial features in pancreatic cancer cells." (PMID 38877560, 2024). "Additionally, KIFC1 depletion led to alterations in the expression of Vimentin, N-cadherin, Bcl-2, E-cadherin, and BAX, suggesting that KIFC1 may contribute to carcinogenesis and progression by influencing apoptosis in pancreatic cancer cells." (PMID 38112634, 2023). "Furthermore, miRNAs belonging to the miR-200 family, such as miR-200a, play a role in regulating stemness in pancreatic cancer by reducing the expression of CSC markers and EMT-related genes such as CD24, CD44, EpCAM, as well as the EMT markers N-cadherin, ZEB1, and vimentin." (PMID 38139352, 2023).
pancreatic cancer (continued). "Tumor cells isolated from pancreatic tumors were analyzed for the expression of the EMT transcription factors Snail 1, Snail 2, Twist 1, Twist 2, Zeb 1, and Zeb 2, the epithelial markers E-cadherin, b-catenin, and Epcam and the mesenchymal markers Vimentin and N-cadherin." (PMID 32174917, 2020). "However, the loss of E-cadherin is usually exclusively found in metastatic lesions and the vimentin is well known for non-specific, frequent coexpression in pancreatic cancers." (PMID 32171280, 2020). "We find that expression of vimentin and E-cadherin, classical markers of epithelial and mesenchymal cells, are strongly anti-correlated at a single-cell level and that malignant tissue is skewed toward EMT, consistent with prior knowledge on the biology of pancreatic cancer." (PMID 29993362, 2018). "In summary, it was identified that through targeting HIF-1α, pancreatic cancer cell proliferation and invasion are inhibited by miR-142; miR-142/ HIF-1α axis regulates hypoxia-induced cell proliferation and invasion through regulation of E-cad, vimentin and VEGF-C." (PMID 28069592, 2017). "Two pancreatic cancer cell lines, PANC-1 (poorly differentiated, high level of Vimentin and low level of E-cadherin) and Capan-1 (well-differentiated, high level of E-cadherin and low level of Vimentin), were used to investigate the correlation between acetyl-DNMT1 and DNMT1 in vivo." (PMID 25960197, 2015). "In pancreatic cancer, the activation of the Hh pathway could induce an EMT, which leads to invasion and metastasis through down-regulating E-cadherin expression and up-regulating vimentin expression." (PMID 23786654, 2013). "Whether or not vimentin expression directly affects the aggressiveness of pancreatic cancer cells because of its functional effects as an intermediate filament or whether it is merely a marker of a more aggressive cancer cell is not known." (PMID 21448168, 2011). "In the short term RNAi experiment, the mRNA level of vimentin was also down-regulated after MBD1 knock-down, indicated that MBD1 may involve in DNA methylation of vimentin and mediate the expression of vimentin in pancreatic cancer." (PMID 18445260, 2008). "Hence, the accurate histology of PDX models is therefore due to that mouse stroma cells are recruited by the pancreatic cancer cells to build up the tumor, which we verified using mouse vimentin staining and lack of human HLA-A, B, C expression (Figure A1 and data not shown)." (PMID 39131259, 2022). "Moreover, although some peptide modifications were found, such as deamination, methylation, phosphorylation and hydroxylation, none were specific to the vimentin isoform that showed reactivity specifically with pancreatic cancer patient’s serum (data not shown)." (PMID 18769604, 2006). "This is because inhibition of SMO by cyclopamine could not reduce vimentin levels, Thus, we speculate that hypoxia enhances EMT and invasion of pancreatic cancer cells through activating a multifaceted factors in which the Hh signaling pathway is a part of an essential network." (PMID 23786654, 2013).